CD4 (CD4 molecule)
Diseases named in the same sentence as CD4 in open-access papers (continued):
Sharing a sentence is not in itself a finding about the gene and the disease.
Atherosclerotic lesion (4 papers, 2018 to 2025). A lesion associated with atherosclerosis, a multifactorial and multipart progressive disease manifested by the focal development within the arterial wall of lesions, that ranges from the development of a fatty streak, plaque progression, and plaque disruption. "It should be noted, however, that loss of CD8+ T cells was compensated by increased CD4+ T cell levels and increased CD4+ T cell infiltrates in atherosclerotic lesions in this study, which may have masked effects of reduced CD8+ T cells on disease progression." (PMID 33383733, 2020). "T cells including CD4+ T cells and CD8+ T cells were found to be increased in atherosclerotic lesions." (PMID 36988256, 2023).
autoimmune thrombocytopenia (4 papers, 2010 to 2025). An autoimmune form of thrombocytopenia. "Together, these data define APOO as a metabolic-transcriptional checkpoint governing CCR7+CD4+ T cell fate, whose repression fosters dysfunctional differentiation and immune imbalance in autoimmune thrombocytopenia." (PMID 41244589, 2025).
autoimmune type 1 diabetes (4 papers, 2016 to 2023). Autoimmune disease wherein the body's own immune system attacks and destroys the cells within the pancreas that produce insulin. "Increased STAT3 (Tyr705) phosphorylation after IL-6 stimulation was recently described in patients with autoimmune type 1 diabetes, and this increased responsiveness was seen both for CD4+ and CD8+ T cells." (PMID 35566660, 2022). "In previous work we showed that a T cell subset described as Th40; CD3+CD4+ helper T cells that express the CD40 receptor, is increased in number in murine autoimmune diabetes and in human autoimmune (type 1) diabetes." (PMID 38318506, 2023).
bare lymphocyte syndrome (4 papers, 2011 to 2023). "Notably this same gene signature is associated with clearance in CD4-replete mice and humans with bare lymphocyte syndrome." (PMID 33491669, 2021). "Patients with MHC class II deficiency generally have severe CD4+ T-lymphocytopenia, hypogammaglobulinemia and lack of antigen-specific antibody responses." (PMID 31921728, 2019). "Patients lacking MHC class II, known as the bare lymphocyte syndrome (BLS), were subjected to severe immune deficiency, and they were devoid of peripheral CD4+ T-cells." (PMID 22028790, 2011).
benign breast tumors (4 papers, 2011 to 2025). "Samples of benign breast tumors and apparently normal breast tissues were used as control.p = 0.041 (control vs. cases)HCMV was associated with a decreased CD4 lymphocytes counts (p = 0.0419)." (PMID 40001942, 2025).
beta thalassemia (4 papers, 2019 to 2023). Beta-thalassemia (BT) is characterized by deficiency (Beta+) or absence (Beta0) of synthesis of the beta globin chains of hemoglobin (Hb). "Post-splenectomized thalassemia major patients have lower monocyte–macrophage numbers, and reduce immuno-globin M (IgM) level, complement system activation, and CD4/CD8 lymphocyte ratio in comparison to non-splenectomized patients." (PMID 36323999, 2023).
Blastocystis infection (4 papers, 2019 to 2025). "Both raising animal and drinking un-boiled water were risk factors for Blastocystis infection, and the interaction of CD4+ T cell count and HIV virus load was also contribution to Blastocystis infection." (PMID 31623666, 2019). "Univariate analysis has revealed that drinking water, raising livestock, HIV infection route, CD4+ T cell count and HIV virus load were closely association with Blastocystis infection." (PMID 31623666, 2019). "Hence, the sample size should be expanded to explore the interaction effect between HIV virus load and CD4+ T cell count during Blastocystis infection in future." (PMID 31623666, 2019). "CD4 + cell count ≤ 500 cells/μl, and an HIV-RNA viral load > 50 copies/ml were the influencing factors of Blastocystis infection in HIV-seropositive individuals." (PMID 33380335, 2020). "In addition, the interaction of CD4+ T cell count and HIV virus load was also contribution to Blastocystis infection (P = 0.007)." (PMID 31623666, 2019).
bleeding disorder (4 papers, 2012 to 2023). "That either CD4 or CD8 antibody treatment prevents death in all LCMV-13 infected FVB mice also supports an immune mediated component in the development of hemorrhagic disease." (PMID 23300439, 2012). "Here, we have examined the role of donor major histocompatibility complex (MHC)-stimulated host CD4+CD25+ regulatory T (Treg) cells in suppressing immune responses against allogeneic uncommitted (Lin−) bone marrow cells (BMCs) for correction of bleeding disorder in HA mice." (PMID 26152192, 2015). "In order to investigate the immune component of the FVB-related hemorrhagic disease further, we depleted either CD4+ or CD8+ cells in FVB mice with anti-CD8 or anti–CD4." (PMID 23300439, 2012).
bowel obstruction (4 papers, 2011 to 2022). "The rise in his CD4 count and the temporal relationship of bowel obstruction to HAART initiation also support the diagnosis of KS-IRIS." (PMID 21791047, 2011). "CD4+ and CD4+/CD8+ were also reduced after relieving the intestinal obstruction." (PMID 28953987, 2017).
brain injury (4 papers, 2017 to 2025). Acute and chronic (see also brain INJURIES, CHRONIC) injuries to the brain, including the cerebral hemispheres, CEREBELLUM, and brain STEM. "Evidence from other acute brain injuries has strongly implicated several major T cell populations in aggravating neuroinflammation and contributing to worsened outcomes, including CD8+ and CD4+ T cells." (PMID 40855747, 2025).
cardioembolic stroke (4 papers, 2015 to 2022). "We should note that a recent study has shown that subjects with cardioembolic stroke had a significantly higher peripheral frequency of CD4+ cells and CD28 null cells (a subtype of T-cells) compared to subjects with other TOAST subtypes." (PMID 27152622, 2016). "Subjects with cardioembolic stroke had a significantly higher peripheral frequency of CD4+ cells and CD28 null cells compared to subjects with other TOAST subtypes." (PMID 25997053, 2015). "Additionally, our study indicated that CLEC4D was positively correlated with neutrophils and T cells CD4 memory activated, while negatively associated with T cells CD8, which implied that CLEC4D might act through an inflammatory mechanism dependent upon immune effectors in cardioembolic stroke." (PMID 35075378, 2022).
carpal tunnel syndrome (4 papers, 2017 to 2020). Entrapment of the median nerve in the wrist that is characterized by numbness, tingling and painful movement. "An increase in central memory CD4+ T lymphocytes is also found in carpal tunnel syndrome, whilst in vivo adoptive transfer of Th1 cells in rats lacking mature T lymphocytes potentiated neuropathic pain symptoms." (PMID 30885223, 2019). "Second, both central and effector memory CD4+ T cells were shown to be significantly increased in chronic neuropathic pain patients with carpal tunnel syndrome (CTS) and complex regional pain syndrome (CRPS), as compared to healthy controls." (PMID 31900220, 2020). "Recently, carpal tunnel syndrome (CTS)—which also needs to be considered in the differential diagnosis of CRPS of the upper limb—was shown to be associated with elevated percentages of central and effector memory CD4+ T-cells which is suggestive of changes in memory T-cell homeostasis in CTS." (PMID 33061828, 2020).
cartilage tumors (4 papers, 2017 to 2021). "We previously demonstrated that Ptpn11 gene deletion driven by CD4 Cre recombinase leads to cartilage tumors in a T cell independent manner since the phenotype is observed even in RAG-1 absence." (PMID 34625577, 2021). "The cartilage tumors in these mice can be detected at approximately the same age as the Shp-2fl/fl-CD4-Cre mice." (PMID 29085371, 2017). "It is therefore likely that the SHP-2/SOS/ERK pathway is critically involved in the regulation of a subset of CD4+ cells, leading to cartilage tumors." (PMID 29085371, 2017). "Unexpectedly, in aging mice, Ptpn11 gene deletion driven by CD4 Cre recombinase leads to cartilage tumors in wrist bones in a T cell-independent manner." (PMID 29085371, 2017). "In addition, CD4-Cre-mediated conditional Sos1/2 or Erk1/2 deletion in chondrocytes resulted in cartilage tumors, which was similar to the cartilage tumors in wrist bones of 6-month-old CD4-CKO mice." (PMID 34764263, 2021). "Importantly, SHP-2fl/fl-CD4-Cre mice on a RAG null background also developed cartilage tumors, ruling out contributions from T cells." (PMID 29085371, 2017). "However, Ptpn11 gene deletion driven by CD4 Cre recombinase leads to cartilage tumors in the wrist." (PMID 34625577, 2021). "PTPN11 deletion in CD4+ cells driven by CD4 Cre recombinase demonstrated that although the ablation of SHP2 does not affect T cell development and functions, it causes cartilage tumors in a T cell-independent manner." (PMID 33777940, 2021). "Surprisingly, in aging mice, Ptpn11 gene deletion driven by CD4 Cre recombinase (but not LckCre) led to cartilage tumors presenting large chondrocyte-like cells and fibrochondrocyte-like cells." (PMID 29085371, 2017). "In the resultant SHP-2fl/fl-CD4-Cre-RAG−/− mice, cartilage tumors developed." (PMID 29085371, 2017).
central nervous system infection (4 papers, 2020 to 2025). "infections, which can cause bacillary angiomatosis, peliosis hepatis, bacteremia, osteomyelitis, central nervous system infections, and infective endocarditis, especially in those with CD4+ cell counts below 50 cells/μL." (PMID 39459894, 2024). "Final diagnosis based on CD4 counts in HIV-infected patients and associated pathogens in episodes of central nervous system infections." (PMID 34603192, 2021).
cervical SILs (4 papers, 2013 to 2025). "Significant proportion of HIV infected women with low CD4 counts have various grades of cervical SIL associated with varieties of uncommon HR genotypes." (PMID 27547239, 2016). "Our study demonstrates that higher CD4+ cell counts are associated with a lower risk of progression to cervical SILs." (PMID 24453469, 2013). "In present study, HIV seropositive women with low CD4 counts and various grades of cervical SIL are significantly infected with HR HPV genotypes." (PMID 27547239, 2016). "Studies on cervical SILs and SCC show predominance of CD4+ or CD8+ cells in the epithelium, stroma or in the lesion as whole, and conflicting associations between the proportion of these T-cell subsets and regression, recurrence or progression have been reported." (PMID 40270290, 2025).
chancre (4 papers, 2012 to 2025). The primary sore of syphilis, a painless indurated, eroded papule, occurring at the site of entry of the infection. "Also CD4+ T lymphocytes were shown to play a key role in chancre formation, since in vivo depletion of CD4+ T cells before inoculation of trypanosomes via a tsetse-fly bite resulted in a significant reduction of chancre formation." (PMID 27446070, 2016). "In contrast to the immunologic events that initially take place in the primary chancres, innate and adaptive immune responses in SS skin lesions appear to co-evolve in the presence of both memory and memory effector CD4+ and CD8+ T cells and high titers of opsonic antibodies." (PMID 22816000, 2012).
Chronic diarrhea (4 papers, 2012 to 2018). The presence of chronic diarrhea, which is usually taken to mean diarrhea that has persisted for over 4 weeks. "In bivariate analysis, factors associated with mortality were: Hgl level <= 8 g/dl, presence of chronic diarrheal disease, CD4 percentage <10% at ART initiation, WHO clinical stage (III&IV) and age less 18 months." (PMID 24517533, 2013).
chronic fatigue syndrome (4 papers, 2011 to 2023). "There is considerable evidence for dysfunction of the CD4+ and especially CD8+ T cells in chronic fatigue syndrome, and given the marked similarity to the symptoms of SARS-CoV-2-induced post COVID fatigue, the pathophysiological role of these T cells in long COVID also arises." (PMID 35214624, 2022).
corneal disease (4 papers, 2012 to 2024). "The first would be that serial reactivation would act as a booster for the pathogenic CD4+ T cells that mediate corneal disease." (PMID 37502845, 2023). "CD4+ Type-1 T lymphocytes (Th1) predominantly secreting interleukin 2 (IL-2) and IFN-γ were shown to induce immunopathology in the course of corneal disease." (PMID 25587898, 2015). "Studies attempting to determine if the classical CD4+ FoxP3+ Treg cells are involved in reducing corneal disease have not conclusively demonstrated that they do so in vivo." (PMID 22593769, 2012). "However, these treated mice did not display an impact on corneal disease, suggesting that naïve CD4+ T cells are being costimulated via B7-1." (PMID 22593769, 2012). "This would lead one to postulate that since CD4+T cells play a central role in the development of HSK58–64, mice that possess an impaired STING pathway would also not display significant corneal disease." (PMID 38514671, 2024). "This would lead one to postulate that since CD4+T cells play a central role in the development of HSK, mice that possess an impaired STING pathway would also not display significant corneal disease." (PMID 37502845, 2023).
Cushing syndrome (4 papers, 2018 to 2025). Cushing's syndrome (CS) encompasses a group of hormonal disorders caused by prolonged and high exposure levels to glucocorticoids that can be of either endogenous (adrenal cortex production) or exogenous (iatrogenic) origin. "Patients with Cushing’s syndrome present lower percentages of CD4 + lymphocytes –the so-called T-helper cells- and increased CD8 + cytotoxic lymphocytes, thus decreased CD4/CD8 ratio, a marker of immune activation." (PMID 39352631, 2025).
cystoisosporiasis (4 papers, 2012 to 2025). "Focusing on immunological parameters, our study confirmed the established association between cystoisosporiasis and reduced CD4+ T-lymphocyte counts <200 cells/μL with an odds ratio of 3.51 (95%CI: 1.42–9.12)." (PMID 40137697, 2025). "A decreased CD4+ T-lymphocyte count <200 cells/μL was proposed as a risk factor for cystoisosporiasis, irrespective of co-occurring antiretroviral therapy, as well as for diarrhea and the abundance of enteric opportunistic pathogens in HIV-positive patients in general." (PMID 40137697, 2025). "Interestingly, the combination of reduced CD4+/CD8+ T-lymphocyte ratios and higher expression of HLA-DR+ CD38+ on CD4+ T-lymphocytes indicated increased immune activation in cystoisosporiasis patients." (PMID 40137697, 2025).
diabetic retinopathy (4 papers, 2015 to 2023). "The co-staining of IL-17, RORγt and CD4 in the retina of diabetic retinopathy showed that Th17 cells infiltrated and damaged the retina during the formation of DR." (PMID 35651615, 2022). "The PD-1+CXCR5+CD4+ GC Tfh cells were expanded markedly both 6 weeks and 12 weeks after STZ injection in the spleen of DR mice, indicating that excess generation and maintaining of Tfh cells were accompanied with the progression of diabetic retinopathy." (PMID 32226551, 2020). "However, at the setting of diabetic retinopathy, many PD-1+CXCR5+ CD4+ Tfh cells with round shape accumulated in the diabetic retina." (PMID 32226551, 2020).
Down syndrome (4 papers, 2022 to 2025). "T cells with partial SNX27 deficiency show a marked deficit in the CD4+ T cell pool, a hallmark of aging in mice and humans, and a well-characterized comorbidity of individuals with Down syndrome (DS)." (PMID 38166948, 2024). "The percentage of naive CD4+ T cells was 33.0 ± 15.51 (mean ± SEM) in children with Down syndrome compared to 60.93 ± 2.53 in healthy controls (p<0.0001)." (PMID 35222360, 2022). "To further examine the role of the AKT signalling pathway in Down syndrome, we performed a phospho-flow assay in T cell subsets (CD3+, CD4+ and CD8+) and B cells (CD20+)." (PMID 35222360, 2022). "For CD4+ T cells, the percentages of PD-1+ and CD244+ expression were elevated in children with Down syndrome (mean 25.9 ± 2.0 and 7.6 ± 1.0, respectively), compared to controls (mean 12.9 ± 1.9 and 4.6 ± 0.9)." (PMID 35222360, 2022). "In conclusion, we showed that children with Down syndrome have hyperphosphorylation of AKT and increased total AKT in B cells and CD4+ T cells." (PMID 35222360, 2022). "The levels of expression of the single receptor CD160+ and co-expression of all three inhibitory receptors, CD4+PD-1+CD160+CD244+ T cells, were similar for children with Down syndrome and healthy controls." (PMID 35222360, 2022). "This subgroup does not include patients on hemodialysis, those receiving non-targeted immunosuppressive therapy, or individuals with Down syndrome, cystic fibrosis, or HIV with CD4 < 200 cells/μL, who are collectively referred to as patients without high-level immunosuppression." (PMID 41150383, 2025).
ductal carcinoma in situ (4 papers, 2017 to 2025). "Spatial analysis of tissue regions revealed tumour niche interactions, including regions enriched for CD4+ T cells and macrophages that were adjacent to invasive tumours but distal to regions of ductal carcinoma in situ (DCIS)." (PMID 39994207, 2025). "This idea is supported by a study showing that higher ratios of FOXP3+CD4+ to CD8+ T cells in biopsies from BC patients with ductal carcinoma in situ predict their relapse." (PMID 29163490, 2017).
EATL type I (4 papers, 2012 to 2024). "An inflammatory background is absent, and necrosis is usually less evident than in classical EATL type I. Immunohistochemically, the tumor cells are CD3+, CD4-, CD5-, CD7+, CD8−/+, CD103+, TCRβ+/−, and contain cytotoxic granule associated proteins." (PMID 23217032, 2012).
enthesitis (4 papers, 2021 to 2025). Inflammation at the site of insertion of ligaments, tendons, and other fibrous structures into bone. "In the very early stages of the disease, which is strongly associated with early enthesitis, IL-17 producing CD4+ Th17 cells, initiate inflammation and may also be involved in sustained inflammation later in disease progression." (PMID 38405187, 2024). "Moreover, CD4-CKO mice showed enthesitis and synovial pannus in bone lesions." (PMID 34764263, 2021). "Additionally, CD4+ and CD8+ T cells at entheses produce IL-17 and TNF-α, contributing to enthesitis." (PMID 40677616, 2025). "We next examined whether the levels of pSTAT3 in Th1 or Tfh cells CD4+ T cells or in CD14+CD16- monocytes were correlated with tender joints (TJ), swollen joints (SJ), enthesitis or C reactive protein (CRP)." (PMID 35087513, 2021).
erythema multiforme (4 papers, 2021 to 2024). Erythema multiforme (EM) refers to a group ofhypersensitivity disorders characterized by symmetric red, patchy lesions, primarily on the arms and legs. "The presence of CD4+ T cells and PD-L1+ keratinocytes in the skin biopsy might be a predictive marker of erythema multiforme major resistant to standard steroid treatment." (PMID 38962048, 2024).